CBR1 (carbonyl reductase 1)
Diseases named in the same sentence as CBR1 in open-access papers (continued):
Sharing a sentence is not in itself a finding about the gene and the disease.
colon cancer (2 papers, 2022 to 2025). "In previous studies, transfection of colon cancer cells (LoVo, DLD1) with CBR1 also lead to mean increase of cell resistance against DOX." (PMID 40629205, 2025).
diabetes (2 papers, 2021 to 2024). "A similar study in mice demonstrated the role of reduced CBR1 gene expression in mouse liver was causative for diabetes and its effects." (PMID 39336582, 2024). "On the contrary, a recent study reported that carbonyl reductase-1 enhances glucocorticoid action and thus causes hyperglycemia and is a risk factor for diabetes and hyperglycemia in mice." (PMID 39336582, 2024). "Cbr1 was identified by RNA sequencing as a key gene involved in the pathogenesis of a streptozotocin-induced rat model of diabetes and is significantly upregulated in the rat heart in diabetes." (PMID 33785425, 2021). "Materials and Methods: Sanger DNA sequencing of the exons of CBR1, GLO1, and ACE genes was conducted in 113 patients with early and severe DN (defined as occurring within 10 years of the diagnosis of diabetes and with eGFR < 45 mL/min/1.73 m2) and 100 controls." (PMID 39336582, 2024).
diabetic nephropathy (2 papers, 2024). "Based on the discussion above it is evident that there was a need to explore polymorphism in more genes related to renal function like GLO-1, CBR-1, and ACE, and look for any association with the development of early severe diabetic nephropathy." (PMID 38545031, 2024). "Methyl glyoxal is metabolized by carbonyl reductase 1 as well, and this enzyme’s reduced activity may lead to an accelerated progression of diabetic nephropathy." (PMID 39336582, 2024). "The affected GLO1 and CBR1 enzymes may lead to the rapid progression of diabetic nephropathy." (PMID 39336582, 2024).
head and neck cancer (2 papers, 2018 to 2020). A primary or metastatic malignant neoplasm affecting the head and neck. "This study will focus the effects of CBR1 on head and neck cancer progression and explore the possible mechanisms." (PMID 31942176, 2020). "Next, to confirm that CBR1 expression indeed influences the results of radiation treatment, we examined whether CBR1 expression is the prognostic factor in 85 patients with head and neck cancer who were treated with radiation therapy." (PMID 30376862, 2018).
osteoarthritis (2 papers, 2017 to 2026). A noninflammatory degenerative joint disease occurring chiefly in older persons, characterized by degeneration of the articular cartilage, hypertrophy of bone at the margins and changes in the synovial membrane. "The main elements of the EC signaling system, including CBR1 and CBR2 mRNA and proteins, were found in synovial biopsies from patients with advanced osteoarthritis and rheumatoid arthritis." (PMID 29110674, 2017).
allergic contact dermatitis (1 paper, 2025). An inflammatory skin condition caused by an immune response to direct contact between the skin and an allergen. "In a mouse model of allergic contact dermatitis, topical THC showed anti-inflammatory activity independent of CBR1 and CBR2 receptors, indicating that THC may have different effects in different tissues due to the involvement of cell-type-specific receptors." (PMID 40141240, 2025).
asthma (1 paper, 2024). "However, although drugs targeting TLR4 and CBR1 proteins have been developed, such as TLR4 (Papain and Cyclobenzaprine) and CBR1 (Heptaethylene glycol and Haloperidol), no drugs have been found for treating childhood asthma." (PMID 38730525, 2024).
childhood asthma (1 paper, 2024). "Based on the genetic data of 4419 (of 4489) plasma proteins from UK Biobank, our study presents compelling evidence linking 10 plasma proteins (GSTO1, LIRB4, PIGF, IL‐21, MICB, PDE4D, RGAP1, TLR4, UBP25 and CBR1) to childhood asthma." (PMID 38730525, 2024). "Elevated levels of seven proteins (TLR4, UBP25, CBR1, Rac GTPase‐activating protein 1 [RGAP1], IL‐21, MICB, and PDE4D) and decreased levels of three proteins (GSTO1, LIRB4 and PIGF) were associated with an increased risk of childhood asthma." (PMID 38730525, 2024).
chronic myelogenous leukemia (1 paper, 2025). "Transfection of chronic myelogenous leukemia K562 cells with the CBR1 gene caused a significant decrease in the cells’ sensitivity to DAUN." (PMID 40629205, 2025).
Cirrhosis (1 paper, 2020). A chronic disorder of the liver in which liver tissue becomes scarred and is partially replaced by regenerative nodules and fibrotic tissue resulting in loss of liver function. "CBR1 antagonists are suggested to have potential of improving cardiovascular activity in cirrhosis, as it was shown that CBR1 contribute to cardiac contractility alterations related to liver cardiomyopathy in cirrhosis rat model." (PMID 33383838, 2020).
colitis (1 paper, 2020). Inflammation of the colon. "CBR1/CBR2 agonists significantly reduce experimental colitis." (PMID 33383838, 2020). "Increased levels of anandamide significantly attenuate colitis in wild-type mice, but not in CBR1 and CBR2-deficient mice." (PMID 33383838, 2020).
colorectal cancer (1 paper, 2020). A primary or metastatic malignant neoplasm that affects the colon or rectum. "CBR1 overexpression is associated with a bad clinical outcome for patients with pancreatic, prostate, ovarian, and colorectal cancers." (PMID 33383838, 2020). "Some data show that low expression of CBR1 in colorectal cancer positively affects the metastatic process, inhibiting apoptosis and deregulating the main signaling pathways." (PMID 33383838, 2020).
cystitis (1 paper, 2021). Inflammation of the urinary bladder. "CBR2 mRNA, but not CBR1 mRNA, increased in acrolein-induced cystitis in rats and lipopolysaccharide (LPS)-induced cystitis in mice." (PMID 34290614, 2021). "Importantly, the non-selective CBR1/CBR2 agonist AZ12646915 reverses the sensitisation of stretch-sensitive afferents in cyclophosphamide-induced cystitis." (PMID 34290614, 2021).
endometritis (1 paper, 2025). An acute or chronic, usually bacterial infectious process affecting the endometrium. "Endometritis in pigs provoked by E. coli changed the contents of PGF2α, elevated the PTGS-2 and PG 9-ketoreductase/carbonyl reductase (CBR1) expression and reduced the expression of PGFS." (PMID 40565335, 2025).
heart failure (1 paper, 2013). Inability of the heart to pump blood at an adequate rate to meet tissue metabolic requirements. "Interindividual variability in CBR1 expression may thus affect the antitumor effect and the risk of DOX-induced heart failure." (PMID 23971034, 2013).
Hypertension (1 paper, 2025). The presence of chronic increased pressure in the systemic arterial system. "Our data suggest that inhibition of CBR1 should be used with caution in those with or susceptible to hypertension." (PMID 39869501, 2025). "PGE2, a substrate of CBR1, is known to induce hypertension and catecholamine release when administered intracerebroventricularly to rats and yet have the opposite effect when given systemically." (PMID 39869501, 2025).
Leber congenital amaurosis (1 paper, 2018). Leber congenital amaurosis (LCA) is a retinal dystrophy defined by blindness and responses to electrophysiological stimulation (Ganzfeld electroretinogram (ERG)) below threshold, associated with severe visual impairment within the first year of life. "This is interesting because mutations in one of the crb human orthologs, CBR1, lead to retinitis pigmentosa (RP12) and Leber Congenital Amaurosis (LCA), which are inherited retinopathies characterized by photoreceptor degeneration and blindness." (PMID 29651238, 2018).
liver cancer (1 paper, 2020). An epithelial or non-epithelial malignant neoplasm that arises from the liver. "Oxidoreductase-peroxiredoxin and carbonyl reductase 1 (CBR1) have been identified among the ESPs of C. sinensis, and both are overexpressed in liver cancer." (PMID 33072014, 2020).
liver disease (1 paper, 2020). "Granulin, thioredoxin peroxiredoxin, carbonyl reductase 1 and cystatin were identified in the C. sinensis proteome and predicted to be related to liver disease and cancer." (PMID 33072014, 2020).
lymph node metastasis (1 paper, 2020). "To test the association of CBR1 with lymph node metastasis (LNM) in HNSCC, we compared the gene expression of CBR1 according to LNM status in HNSCC patient cohorts from publicly available data." (PMID 31942176, 2020).
macular degeneration (1 paper, 2012). Loss of vision in the central portion of the retina (macula), secondary to retinal degeneration. "One case has only a single ABCA4 mutation, one has a variant of unknown significance in CBR1 and one sample has no demonstrable mutations in any gene with known association to retinal or macular degeneration." (PMID 22863181, 2012).
melanoma (1 paper, 2022). A malignant, usually aggressive tumor composed of atypical, neoplastic melanocytes. "In Human Melanoma Cell Line (SK‐mel‐1) extracts, CBR1 had only a band with a molecular mass of 37 kDa, whereas the reactivity for anti‐CB2 antibody had 2 bands of approximately 40 and 70 kDa, respectively." (PMID 35801813, 2022).
metastatic tumors (1 paper, 2020). "Hence, it is unknown whether CBR1 affects ROS-mediated EMT leading to metastatic tumors in HNSCC; however, it is likely because CBR1 is a key regulator of oxidative molecules." (PMID 31942176, 2020).
migraine (1 paper, 2023). "Results from a genetic study demonstrated a significant haplotypic effect of CNR1 (the gene of CBR-1) on headaches with migraine symptoms (e.g., nausea, photophobia, disability) only when using extreme trait combinations (0 symptoms versus 3 symptoms)." (PMID 36835524, 2023).
neuroblastoma (1 paper, 2022). Neuroblastoma (NB) is the most common solid, extracranial childhood tumor. "To establish a model system in which the role of CBN in neuroblastoma biology can be explored, we examined the expression levels of cannabinoid receptors, including CBR1 and CBR2, in normal and neuroblastoma cell lines." (PMID 35454815, 2022). "Western blot analysis showed that CBR1 and CBR2 were differentially expressed in the indicated normal and neuroblastoma cell lines." (PMID 35454815, 2022).
non‐alcoholic steatohepatitis (1 paper, 2024). "The first biologic drug targeting the ECS, namacizumab, a negative allosteric modulating antibody (NAMA) that stabilizes CBR1 in an inactive conformation, was approved to initiate a phase 1 of the clinical trial in the treatment of non‐alcoholic steatohepatitis (NASH) and diabetic nephropathy." (PMID 39292202, 2024).
placental disorders (1 paper, 2024). "Furthermore, based on a study conducted in humans, it seems that a decrease in CBR1 and CBR1a mRNA levels might be connected with placental disorders, such as preterm placental abruption, leading to preterm deliveries or the intrauterine death of the fetus." (PMID 38745869, 2024).
prostate carcinoma (1 paper, 2021). A carcinoma that arises from epithelial cells of the prostate gland. "In comparison, other studies observed in prostate cancer that CBR1 expression was positively correlated with the epidermal growth factor receptor (EGFR) (rs = 0.316, p < 0.001)." (PMID 34575629, 2021). "Indeed, high CBR1 and/or CBR2 expression has been shown to be associated with survival in prostate cancer and colorectal cancer." (PMID 34575629, 2021).
renal fibrosis (1 paper, 2021). A final common manifestation of a wide variety of chronic kidney diseases characterized by glomerulosclerosis and tubulointerstitial fibrosis. "As for the specific genes enriched in different cell types of IRI-induced renal fibrosis, CBR1 was mainly expressed in tubule cells and some types of immune cells." (PMID 34777334, 2021).
Sepsis (1 paper, 2023). Sepsis is defined as life-threatening organ dysfunction caused by a dysregulated host response to infection. "Recent reports have documented a range of beneficial effects of FFA beyond its direct anti-inflammatory activity, including its ability to promote carbonyl reductase 1 (CBR1) upregulation and thereby protect against pulmonary damage induced by sepsis." (PMID 36971552, 2023).
type II diabetes (1 paper, 2021). "FDA-approved acetohexamide currently used to treat type II diabetes can be used as an activator of CBR1." (PMID 33692493, 2021).
vitamin D deficiency (1 paper, 2020). A nutritional condition produced by a deficiency of VITAMIN D in the diet, insufficient production of vitamin D in the skin, inadequate absorption of vitamin D from the diet, or abnormal conversion of vitamin D to its bioactive metabolites. "We observed that the Nrf2 and CBR1 protein levels were all significantly decreased vitamin D deficiency group compared with control group." (PMID 32184720, 2020).
cancer (24 papers, 2010 to 2025). A tumor composed of atypical neoplastic, often pleomorphic cells that invade other tissues. "CBR1 expression levels in tissues have been shown to influence cancer cell sensitivity, drug pharmacokinetics, and the risk of cardiotoxicity." (PMID 40629205, 2025). "Despite their clinical efficacy, their use is limited by cancer cell resistance, linked to the formation of secondary alcohol metabolites via carbonyl reductase 1 (CBR1)-mediated reduction." (PMID 40629205, 2025). "In this study, an effort was made to fill gaps in knowledge regarding differences in anthracycline susceptibility to the CBR1-dependent mechanism of cancer cell resistance." (PMID 40629205, 2025). "The Asp551-p85β, equivalent to Asp560-p85α (mutated to tyrosine in cancer), interacts with the Ser457 and Ser458 in the Cβ7/Cβ8 loop from the C2 domain and possibly also with the poorly ordered CBR1 loop." (PMID 21362552, 2011). "In this study, a cellular model was developed to investigate the role of CBR1 in cancer cell resistance." (PMID 40629205, 2025). "The study aimed to elucidate the role of CBR1 in mediating the differential responses of various anthracyclines in cancer cells." (PMID 40629205, 2025). "While CBR-1 generally supports angiogenesis, it can also contribute to pathological conditions like cancer, where excessive angiogenesis can support tumor growth and metastasis." (PMID 39707578, 2024). "CBR1 plays a critical role in tumor metastasis and growth and its expression level is elevated in cancer tissues compared with paired normal lung tissue." (PMID 35957912, 2022). "For validation, we compared the expression of CBR1 protein in cancer tissue of 36 patients with HNSCC using IHC." (PMID 31942176, 2020). "Hypoxia induces doxorubicin resistance by increasing the expression of carbonyl reductase 1 (CBR1), an enzyme that converts doxorubicin into a less effective form, in cancer cells." (PMID 30791624, 2019). "Suppression of HIF-1α-induced CBR1 by resveratrol (10 μM) increased the sensitivity of hypoxic breast cancer cells to doxorubicin, making the hypoxic cancer cells sensitive to doxorubicin as shown in normoxic cancer cells." (PMID 30791624, 2019). "The potential of FLU to inhibit reduction of the anticancer drug DOX (known CBR1 substrate) was tested in the human liver and in cancer cells SW480." (PMID 31191322, 2019). "Several genes involved in the GESGC have been reported to be associated with human cancer, including LOXL1, RAB31 and CBR1." (PMID 29957874, 2018). "Stable overexpression of GSTP1 and CBR1 in cancer cells also reduces PL-induced ROS levels and rescues apoptosis." (PMID 25193861, 2014). "The mechanism of these endocannabinoid-targeting drugs varies based on the type of cancer and the receptor, CBR-1, CBR-2, transient receptor potential vanilloid TRPV1 or TRPV2, and whether it is dependent or independent." (PMID 39707578, 2024). "In addition to AKR1B1 and AKR1B10, in human chemoresistant cancer cell lines also carbonyl reductase 1 (CBR1) is upregulated and partially responsible for the resistance." (PMID 35328588, 2022). "Our data suggest that these variations may have important consequences for an individual's glucocorticoid metabolism and metabolic health and that these consequences should be considered when manipulating CBR1 for other reasons such as cancer treatment." (PMID 33785425, 2021). "In addition, IHC in tissues indicated that patients with LNM had relatively lower levels of CBR1 in cancer tissue." (PMID 31942176, 2020). "A SNP in CBR1 increased DOX-related risk of cardiomyopathy, while other SNPs were associated with significantly increased DOX exposures in a population of Asian cancer patients." (PMID 28283780, 2017). "We speculate the possibility that PL inhibits GSTP1 or CBR1 activity and caused ROS accumulation, which in turn oxidized intracellular thiol-containing antioxidant agents like GSH and Trx, thus sensitized the cancer cells to AF-induced apoptosis." (PMID 26431378, 2015).
cancer (continued). "In this study, novel resistance mechanism of cancer cells against ACLA was proposed; therefore, CBR1 expression level and activity should be considered in studies investigating ACLA anticancer activity." (PMID 40629205, 2025). "After in silico evaluation, the inhibitory activity was assessed in studies with recombinant CBR1 proteins, and then, the cytotoxic effect of simultaneous administration of DNR and ASP9521 was determined on A549 cancer cells." (PMID 37175180, 2023). "Structurally, ASP9521 possesses similar features to known CBR1 inhibitors, e.g., luteolin and cinnamamide derivatives, which have previously been described as compounds potentiating ANT activity against cancer cells." (PMID 37175180, 2023).